FANCI (FA complementation group I)
Description:
Plays an essential role in the repair of DNA double-strand breaks by homologous recombination and in the repair of interstrand DNA cross-links (ICLs) by promoting FANCD2 monoubiquitination by FANCL and participating in recruitment to DNA repair sites. The FANCI-FANCD2 complex binds and scans double-stranded DNA (dsDNA) for DNA damage; this complex stalls at DNA junctions between double-stranded DNA and single-stranded DNA. Participates in S phase and G2 phase checkpoint activation upon DNA damage.
Synonyms: KIAA1794; FLJ10719
Tractability: Small molecule: a structure with a bound ligand is known. PROTAC: UniProt records ubiquitination sites on it; ubiquitination databases record sites on it.
Target class: Other nuclear protein
Safety:
Unwanted effects reported when the protein is acted on. In parentheses: how it was acted on, where the effect was seen, and who reports it.
hepatotoxicity (source: ClinPGx)
Gene: Protein-coding gene on chromosome 15 (89,243,854 to 89,318,091, forward strand). Ensembl gene ENSG00000140525.
Subcellular location: Nucleus; Cytoplasm
Subcellular location (Human Protein Atlas): Nucleoplasm
Pathways (Reactome):
DNA Repair: Fanconi Anemia Pathway
Gene Ontology:
Molecular function: DNA polymerase binding; protein binding
Biological process: positive regulation of protein ubiquitination; interstrand cross-link repair; DNA repair
Cellular component: cytoplasm; DNA repair complex; membrane; nucleoplasm; chromatin; nucleus
Genetic constraint (gnomAD): Loss-of-function variants: 128 observed, 154.51 expected, observed/expected ratio (o/e) 0.83, 90% interval 0.72 to 0.96. The upper end of that interval is the gene's LOEUF score, 0.96, which puts it in group 4 of 6, group 1 being the genes least tolerant of losing a copy. Missense variants: 1,581 observed, 1,507.5 expected, observed/expected ratio (o/e) 1.05, 90% interval 1 to 1.09. Synonymous variants: 574 observed, 539.84 expected, observed/expected ratio (o/e) 1.06, 90% interval 0.99 to 1.14.
Gene-disease validity (ClinGen):
ClinGen rates the evidence that FANCI causes each of these diseases.
Fanconi anemia complementation group I (autosomal recessive): Definitive. Fanconi anemia caused by mutations in the FANCI gene, encoding Fanconi anemia group I protein.
Cancer hallmarks: proliferative signalling (promotes); genome instability and mutations (suppresses); escaping immune response to cancer; escaping programmed cell death (promotes); invasion and metastasis (promotes )
Homologues: Orthologues: chimpanzee FANCI (99% identical), macaque FANCI (97% identical), dog FANCI (88% identical), rabbit FANCI (87% identical), pig FANCI (87% identical), guinea pig FANCI (82% identical), rat Fanci (81% identical), mouse Fanci (81% identical), tropical clawed frog fanci (66% identical), zebrafish fanci (60% identical), Drosophila melanogaster FANCI (22% identical), Caenorhabditis elegans fnci-1 (18% identical).
Diseases named in the same sentence as FANCI in open-access papers:
FANCI is named in the same sentence as 88 diseases in open-access papers, as found by Europe PMC text mining. Sharing a sentence is not in itself a finding about the gene and the disease. The quoted sentences say what the papers report.
Fanconi anemia (99 papers, 2008 to 2026). Fanconi anemia (FA) is a hereditary DNA repair disorder characterized by progressive pancytopenia with bone marrow failure, variable congenital malformations and predisposition to develop hematological or solid tumors. "The FANCI gene, an essential element of the Fanconi anemia pathway, has been associated with a variety of cancer types." (PMID 40417238, 2025). "FAAP20 is a Fanconi anemia (FA) protein that associates with the FA core complex to promote FANCD2/FANCI monoubiquitination and activate the damage response to interstrand crosslink damage." (PMID 37620397, 2023). "We reported the discovery of FANCI c.1813C>T; p.L605F in two siblings in family F1528 as the most plausible OC-predisposing candidate based on the association of FANCI in the Fanconi anemia homologous recombination (FA-HR) DNA repair pathway." (PMID 36833203, 2023). "The biallelic germline mutations of BLM and FANCI resulted in Bloom syndrome and Fanconi anemia (FA), respectively, characterized by congenital disabilities and cancer predisposition." (PMID 35860547, 2022). "FANCI is a well-known pathogenic gene for the Fanconi Anaemia (FA), a progressive bone marrow failure syndrome that affects DNA repair process and increases cancer risk, including AML." (PMID 35280783, 2022). "Mutations in FANCI of familial colorectal cancer that regulate DNA repair and were associated with the Fanconi anemia repair pathway." (PMID 36428813, 2022). "FANCI is a Fanconi anemia (FA) protein and mutations in FA genes predispose to tumor development, as shown not only for hereditary breast and ovarian cancer, but also for early-onset/familial prostate carcinoma and acute myeloid leukemia." (PMID 34573422, 2021). "Mutations in genes that regulate DNA repair (RMI1, PALB2, FANCI) were identified that were related to the Fanconi anemia DNA repair pathway." (PMID 34549727, 2021). "Pathogenic mutations were also common in Fanconi Anemia associated gene (FANCI, 12.5%) known to play a significant role in repairing double-stranded DNA breaks by homologous recombination and restoring inter-chain DNA crosslinks." (PMID 31428572, 2019). "Missense, nonsense and splice-site variants in the FANCI gene underlie ∼2% of Fanconi anemia (FA) cases in human." (PMID 22952632, 2012). "Notably, we detected germline pathogenic variant in Fanconi anemia (FA) complementation group I (FANCI) and group G (FANCG), which are involved in repairing DNA double-strand breaks by homologous recombination, for the first time, in ECS blood samples." (PMID 39158654, 2024). "One sporadic melanoma MITF-E318K carrier resulted wild-type for CDKN2A and MC1R genes and displayed only germline variants of unknown significance in ATM and Fanconi anemia complementation group I (FANCI) genes." (PMID 34573422, 2021). "The REF values for such proteins as ERLIN2 (ER membrane lipid raft-associated 2), FANCI (Fanconi anemia complementation group I) and BAG2 (BAG family molecular chaperone regulator 2) were 0.72, 0.72 and 0.3 in only AIMP2 immunoprecipitates unlike those of AIMP1 and KARS." (PMID 24312579, 2013). "The remaining genes, such as GLYCTK, DRD5, NPHP3, and FANCI, were well-characterized pathogenic genes for some other rare diseases with recessive mode of inheritance or multi-gene diseases, such as D-glyceric aciduria, attention deficit-hyperactivity disorder, Meckel syndrome, and Fanconi Anemia." (PMID 30693022, 2018). "Mutations in the Fanconi anemia (FA) pathway were present in 33.3% of patients, predominantly involving FANCA, FANCI, and FANCG." (PMID 40805139, 2025). "FANCI (Fanconi anemia complementation group I) is a critical gene involved in the DNA damage response and repair pathways, particularly within the Fanconi anemia (FA) pathway." (PMID 40417238, 2025). "While Fanconi Anemia-associated genes BRCA2, FANCA and PALB2 are known PCa GT candidates, FANCD2 outranked FANCA, with FANCG, ECCR4, FANCE and FANCI (in order of ranking) potential candidates." (PMID 41038821, 2025).
Fanconi anemia (continued). "FANCI is a critical component of the Fanconi anemia pathway, a classical DNA damage repair mechanism." (PMID 40832468, 2025). "Well-characterized substrates of USP1 include FANCD2 and FANCI, key components of the Fanconi anemia DNA repair pathway, as well as PCNA, which plays a central role in DNA replication and repair." (PMID 40940964, 2025). "Among such proteins whose expression is worth studying in ovarian cancer are BRIP1 (BRCA1 interacting protein C-terminal helicase 1) and also FANCI (Fanconi anemia complementation group I)." (PMID 39767562, 2024). "In cells expressing the p.L605F isoform, there was a significant reduction in the localization of FANCD2, a component of the FANCI-FANCD2 (ID2) binding complex in the Fanconi anemia (FA) pathway, to sites of induced DNA damage." (PMID 39767562, 2024). "FANCI is a critical contributor to Fanconi anemia complex function in DNA damage response, and we have previously implicated FANCI as a potentially important mediator of treatment resistance in prostate cancer." (PMID 38023254, 2023). "USP1 targets FANCD2/FANCI to regulate the Fanconi anemia pathway (FA) and, together with USP7, targets translesional DNA repair (TLS)." (PMID 37892185, 2023). "Our results reveal that FANCI depletion results in significant downregulation of Fanconi anemia (FA) pathway members in prostate cancer cells, indicating that FANCI is an important regulator of the FA pathway." (PMID 38023254, 2023). "An important finding is that FANCI, a protein involved in Fanconi anemia, interacts with proteins that function in ribosome biogenesis, the process of synthesizing ribosomes in cells, in addition to DNA repair." (PMID 37566603, 2023). "FANCI, a member of the Fanconi anemia (FA) DNA repair pathway involved in the repair of interstrand crosslinks, was shown to have abrogated function in cells expressing p.L605F." (PMID 36833203, 2023). "Another interesting finding in our cohort is the high incidence of monoallelic variants in other Fanconi anemia (FA) genes: FANCA, FANCC, FANCD2, RAD51C, FANCG and FANCI." (PMID 36290365, 2022). "We also found specific upregulation of genes of the Fanconi anemia pathway, in particular FANCM, FANCD2 and FANCI, which encode known interaction partners of BLM." (PMID 35099000, 2022). "Germline mutation detection showed that nine variants associated with Fanconi anemia (VAFAs) pathway (FANCA, 6/18; FANCI, 3/18) were identified in 18 ccpRCC patients." (PMID 34512202, 2021). "FANCI, one gene of the Fanconi anemia complementation group, alternative splicing results in two transcript variants encoding different isoforms." (PMID 33190424, 2021). "Among this, we found 3 mutations related to the Fanconi anemia (FA) DNA repair pathway (RMI1, PALB2, FANCI)." (PMID 34549727, 2021). "FANCD2 and FANCI are critical proteins that are mono‐ubiquitylated as part of the activation process within the Fanconi anaemia (FA) pathway, which is required for the repair of inter‐strand crosslinks (ICLs)." (PMID 33625522, 2021). "In COAD, we found FANCI, which plays a role in Fanconi anemia pathway, as an interacting partner of FANCD2 (down, ferroptosis negative regulator)." (PMID 33670487, 2021). "FANCD2 and FANCI are ubiquitylated by the Fanconi anemia core complex in a site-specific manner upon recruitment to chromatin during the repair of inter-strand crosslinks." (PMID 33348378, 2021). "Localization of FANCD2, part of the FANCI-FANCD2 (ID2) binding complex in the Fanconi anaemia (FA) pathway, to sites of induced DNA damage was severely impeded in cells expressing the p.L605F isoform." (PMID 34861889, 2021). "FANCI is an essential component of Fanconi anemia pathway, which is responsible for the repair of DNA interstrand cross-links (ICLs)." (PMID 34373449, 2021).
Fanconi anemia (continued). "FANCI has a key role in the Fanconi anemia DNA repair pathway, where it forms a heterodimer with FANCD2 and recruits DNA repair proteins to promote the interstrand cross-link DNA damage repair." (PMID 33868991, 2021). "We detected germline variants in genes associated with Fanconi anemia in eight patients with ccpRCC (FANCA, 6/18; FANCI, 3/18)." (PMID 34512202, 2021). "FAN1 encodes Fanconi anemia-associated nuclease 1 (FAN1), which interacts with Fanconi Anemia Complementation group D2 (FANCD2) and Fanconi Anemia Complementation group I (FANCI), forming the Fanconi Anemia core complex." (PMID 34126972, 2021). "Most detected variants affected the Fanconi anemia/DNA repair pathway (34%, ATM, FANCA, FANCI, MLH1, MSH6, POLE, RAD51C, RAD51D) followed by mutations altering the SWI/SNF (SWItch/sucrose non-fermentable) complex (22%, ARID1A and SMARCA4)." (PMID 34200508, 2021). "Deubiquitination of FANCD2 and FANCI appears to be as important as ubiquitination, in the regulation of the Fanconi Anemia pathway." (PMID 32117957, 2020). "Here we identified that RPS27L binds to FANCD2 and FANCI, two Fanconi anemia (FA) proteins functioning in ICL repair pathway." (PMID 33051438, 2020). "Fanconi anemia (FA) complementation group I (FANCI) is a gene belonging to the FA–breast cancer pathway, and the mono-ubiquitination of the FANCI–FANCD2 protein complex is the key to the normal function of the FA pathway." (PMID 32582275, 2020). "FANCI:FANCD2 monoubiquitination is a critical event for replication fork stabilization by the Fanconi anemia (FA) DNA repair pathway." (PMID 32167469, 2020). "Altogether, these results suggest that there is an increase in R-loop formation in RNF2 KO cells, and the Fanconi Anemia proteins FANCD2 and FANCI are necessary to prevent the R-loop-associated genomic instability in RNF2 KO cells." (PMID 32142505, 2020). "Among these, FANCD2, FANCI and other proteins of the Fanconi Anemia complex were highly enriched, including APITD1, also known as CENPS, which promotes mono-ubiquitination of FANCD2-FANCI in response to DNA damage." (PMID 31180492, 2019). "WES revealed that HMCLs displayed frequent mutations in Fanconi anemia genes (PALB2 [12%], FANCI [12%], FANCA [9%], FANCD2 [9%], BRCA2 [9%]) as well as in helicases (such as RECQL4, 15%, and BLM, 15%) and epigenetic modifiers (e.g., TET2, 15% and SETD2, 6%)." (PMID 30545397, 2018). "Six patients had mutations in FANCA, FANCI, FANCL, FANCM and SLX4 genes, which are involved in Fanconi anemia (FA)." (PMID 28423363, 2017). "Proteins other than BRCA2 implicated in homologous recombination or the Fanconi anemia repair pathway, like BRCA1, RAD51, PALB2, XRCC3, FANCI, or FANCD2, were at most modestly affected, as were non-homologous end joining proteins like KU80, KU70, and XRCC4." (PMID 28575672, 2017). "FANCI is part of the Fanconi anaemia complementation (FANC) gene family, which are mutated in Fanconi anaemia and participate in DNA repair." (PMID 26798408, 2016). "In the Fanconi anemia DNA repair pathway, SUMO interaction motifs (SIMs) of the FANCI protein associate with sumo-like domains (SLDs) within the WDR48 C-terminus." (PMID 25855980, 2015). "We show that central components of the Fanconi anemia (FA) DNA repair pathway, the tumor suppressor proteins FANCI and FANCD2 (the ID complex), are SUMOylated in response to replication fork stalling." (PMID 25557546, 2015). "One of Fanconi anemia (FA) proteins, FANCI forms a functional heterodimer by interacting with FANCD2 (Fanconi anemia group D2) and the complex is recruited to the branched DNA structures." (PMID 24312579, 2013). "FANCI is a gene that belongs to the Fanconi anemia complementation group which is related to DNA repair." (PMID 23762400, 2013). "Here, we report our findings that six Fanconi Anemia (FA) proteins, including FancI and FancJ, localize to the centrosome." (PMID 24167712, 2013). "FANCI is a critical component of the Fanconi anemia pathway." (PMID 40417238, 2025).
Fanconi anemia (continued). "This is highly consistent with FANCI’s known role in the Fanconi anemia pathway." (PMID 40417238, 2025). "FANCI is part of the Fanconi anemia pathway, which is vital for interstrand cross-link repair." (PMID 39795882, 2024). "Moreover, 14% of the patients included in this study harbored deleterious mutations in Fanconi anemia genes (FANCA, FANCD2, FANCF, FANCG FANCI and FANCL) and in WRN, which have been reported to interact with BRCA1." (PMID 38184614, 2024). "Interestingly, germline mutation rate of members of the Fanconi anaemia family of genes (including BRCA2, PALB2, BRIP1, RAD51C, FANCA, FANCI and FANCL) was 53.4% (31/58) among the patients with germline mutations in our cohort." (PMID 32091409, 2020). "FANCD2/FANCI mono-ubiquitylation promotes retention of the core Fanconi anaemia complex on damaged chromatin and has been shown to be an essential step in coordinating recruitment of a number of key proteins to ICL repair sites, including the nuclease FAN1 and CtIP." (PMID 25833379, 2015). "The Fanconi anaemia (FA) pathway constitutes a central genome maintenance system that orchestrates the repair of DNA interstrand crosslinks (ICLs) through the coordinated monoubiquitination of FANCI and FANCD2, followed by recruitment of repair effectors such as BRCA1, REV1, and ERCC1." (PMID 41486508, 2026). "The actions of UL138 are due, in part, to its modulation of pathways regulated by the cellular deubiquitinating complex that targets proliferating cell nuclear antigen (PCNA) and Fanconi Anemia effectors, FANCD2 and FANCI." (PMID 41533576, 2026). "Six hub genes (FANCI, KAT2A, TACC3, TPX2, VHL, WSB1) were enriched in Fanconi anemia and HIF-1 pathways, affecting microtubules, spindle formation, and cytoskeleton dynamics during mitosis." (PMID 40832468, 2025). "Pathway analyses with the KEGG and REAC databases revealed a significant enrichment of the Fanconi anemia (FA) repair pathway, with notable genes such as BRIP1 (FANCJ), FANCI, FANCA, SLX4 (FANCP), UBE2T (FANCT), and C19orf40 (FAAP24)." (PMID 38896450, 2024). "Di‐monoubiquitination of the FANCI‐FANCD2 (ID2) complex is a central and crucial step for the repair of DNA interstrand crosslinks via the Fanconi anaemia pathway." (PMID 36385258, 2023). "Similar to FBXL21 ubiquitinating MYOZ1 and TCAP, another E3 ligase, the FANCL subunit of the FA (Fanconi anemia) core complex, has been shown to monoubiquitinate two interacting proteins, namely FANCD2 and FANCI." (PMID 36574402, 2022). "HRR alterations involve Fanconi anemia genes (PALB2, FANCA, FANCL, FANCI, FANCC), core RAD genes (RAD50, RAD51, RAD51B, RAD51C) as well as DNA damage response genes (ATM, ATR, CHEK1, CHEK2)." (PMID 36531003, 2022). "On the other hand, UBE2T is the E2 ubiquitin-conjugating enzyme for the Fanconi Anemia pathway and monoubiquitinates several proteins of the pathway, that also appeared in our screening like FANCD2 and FANCI." (PMID 33925616, 2021). "In summary, we reported here a novel connection between a ribosomal protein and Fanconi anemia proteins, demonstrating that RPS27L binds to and stabilizes FANCD2 and FANCI." (PMID 33051438, 2020). "Our work also suggests that direct modulation of FANCI phosphorylation plays a twofold role in stabilizing FANCD2 monoubiquitination, with relevance to understanding and treating both Fanconi anemia and cancer." (PMID 32117957, 2020). "An important mechanism for the removal of ICLs is the Fanconi Anemia DNA repair pathway, which is initiated by mono-ubiquitination of FANCD2 and its partner protein FANCI." (PMID 32117957, 2020).